EGFR (epidermal growth factor receptor)
Diseases named in the same sentence as EGFR in open-access papers (continued):
Sharing a sentence is not in itself a finding about the gene and the disease.
tumor (continued). "We found that increased EGFR expression and AKT (pS473) phosphorylation were significantly associated with tumor size in T3-T4 stage patients." (PMID 28881811, 2017). "Pathological reports revealed that the nature of tumor was poorly differentiated adenocarcinoma with differentiation markers of cholangiocyte; in addition, moderate EGFR expression was detected in >90% tumor cells." (PMID 28057014, 2017). "Recently, several retrospective, unplanned analyses examined primary tumor sidedness and revealed that anti-EGFR therapy clearly benefitted patients with LCRC, whereas patients with RCRC derived limited benefit." (PMID 29212173, 2017). "It utilizes EGFR-Sp1 signaling to maintain mucin levels as an alternate tumor suppressive pathway in CAC." (PMID 29212256, 2017). "The purpose of our study was to explore the effect of baseline serum tumor markers in stage IIIB/IV NSCLC patients treated with EGFR-TKIs." (PMID 29050327, 2017). "Among 54 patients having RAS wt tumor tissue, 34 were treated with anti-EGFR monoclonal antibodies (31 with cetuximab and 3 with panitumumab-based regimens; 30 plus chemotherapy and 4 in monotherapy)." (PMID 28419195, 2017). "Measuring the concentrations of EGFR TKIs in CSF therefore has limited utility in determining drug concentrations within tumor cells." (PMID 29228726, 2017). "The three patients who were tumor-tissue EGFR M- but plasma cfDNA EGFR M+ had PFS times of 133, 410, and 1,153 days, respectively, after EGFR-TKI treatment." (PMID 28052016, 2017). "Tumor cells that survived up to 6–9 days of erlotinib treatment signaled independently of EGFR and MET with early STAT3 reactivation." (PMID 28521301, 2017). "IHC (immunohistochemistry) revealed a Brachyury, PDGFR-β and EGFR 2+ positive tumor (R pharmDxTM Dako kit) with evidence of pS6 phosphorylation in more than 70% of cells." (PMID 28775967, 2017). "RAS and BRAF wild type tumours frequently respond to anti-EGFR therapy, whereas mutant tumours are refractory due to primary resistance." (PMID 28120820, 2017). "In this case vaccination of animals with the ECD of autologous EGFR overcame the tolerance to self-EGFR, promoting highly specific IgG titers capable to inhibit EGFR+ tumor cell growth in vitro." (PMID 28539888, 2017). "Increase of EGa1 on liposomes from 0.4 to 0.8 nmol can even lower the EGFR levels and further enhances the inhibition of tumor growth." (PMID 29163515, 2017). "Tumor formation was also observed in 5 of the 7 mice with cells that overexpressed full-length EGFR gene, although their tumor size was smaller than fusion gene-overexpressing cells." (PMID 28978917, 2017). "The two RITs are designed to simultaneously target both the EGFR that are overexpressed on cancer cells and the uPAR on tumor neovasculature." (PMID 28752098, 2017). "Our results showed that both uPAR and TF had high positive expression rates and tumor-specific expression patterns while EGFR also had regular expression in normal tissues." (PMID 28841839, 2017). "Blockade of EGFR with specific tyrosine kinase inhibitors (TKIs) can generate dramatic tumor responses in NSCLC." (PMID 28430586, 2017). "Tumor specimen HN15-062 expressing negligible amount of EGFR is shown as control for the specificity of the ubiquitylated EGFR signal." (PMID 29268862, 2017). "The rational of this vaccine-based immunotherapy was to stimulate an anti-EGFR immune response against EGFR- expressing tumor cells with minimally collateral damage to normal tissues." (PMID 28539888, 2017). "Administration of cRGD-siEGFR to tumor-bearing nude mice led to significant inhibition of tumor growth, obvious reduction of EGFR expression and down-regulation of EGFR mRNA and protein in tumor tissue." (PMID 28181832, 2017). "Among the different materials derived from liquid biopsies, ctDNA has been successfully applied to detect EGFR mutations in NSCLC patients and can give similar molecular information as those given by invasive tumor biopsies." (PMID 28146051, 2017).
tumor (continued). "We here demonstrate that anti-EGFR-GNs is a useful therapeutic strategy for applying EGFR-targeted NIR-PTT to aggressive TNBC due to their properties of selective tumor cell targeting, long circulation time and desired optical absorption upon NIR irradiation." (PMID 29156817, 2017). "Because of superior antitumoral activity of hexavalent TNF-related apoptosis-inducing ligand (TRAIL) formats and the advantage of a tumor-targeted action, we choose expression of a dimeric EGFR-specific diabody single-chain TRAIL (Db-scTRAIL) as a model." (PMID 28553285, 2017). "The aim is to inhibit the immune checkpoint, while either simultaneously suppressing the inflammatory responses (blocking IL-1b or IL-17), or inhibiting tumor cell proliferation with mitogen-activated protein kinase and EGFR inhibitors." (PMID 29312320, 2017). "Combination of Met and Erlo exhibited a greater effect to inhibit phosphorylation of EGFR significantly than Erlo or Met alone in the xenograft tumor tissues seen 30 days after tumor cell implantation." (PMID 29312591, 2017). "We confirmed that its efficacy depended on the inhibition of phosphorylation of EGFR and the decreased expression of EGFR itself in western blotting of tumour samples obtained from each treatment group." (PMID 28287083, 2017). "Here, we find that LOX regulates the epidermal growth factor receptor (EGFR) to drive tumour progression." (PMID 28416796, 2017). "The results from dose escalation showed a dose-dependent ABY-029 tumor uptake, which can be related to saturation of EGFR in the liver." (PMID 27379987, 2017). "Consistent with the previous results, tumor tissues showed more positive staining of EGFR, K-Ras, p-B-Raf, p-MEK and p-ERK1/2 compared with the normal colon tissues." (PMID 27926503, 2017). "As many studies have reported, MMPs play a predominant role in the process of tumour cell intravasation, and the dynamic interplay between N-cadherin and epidermal growth factor receptor (EGFR) leads to MMPs gene transcription." (PMID 28545547, 2017). "Surprisingly, erlotinib—another EGFR inhibitor—decreases hypoxic regions in tumor tissues and induces vascular normalization in tumors, which, in turn, improves the efficacies of chemotherapy and radiotherapy." (PMID 27999195, 2017). "To exploit this concept we designed a study to investigate the influence of HT on the anticancer efficacy of cetuximab, a monoclonal antibody against EGFR known to produce EGFR downregulation, and the ensuing tumor growth inhibition and cell apoptosis." (PMID 29137335, 2017). "Conversely, the anti-tumour activity of single-targeted ErbB agents including cetuximab (a ligand-blocking anti-EGFR mAb), transtuzumab (anti-HER2 mAb), H3.105.5 (anti-HER3 mAb) and erlotinib (EGFR small-molecule tyrosine kinase inhibitor) were marginal." (PMID 28646172, 2017). "EGFR is an oncogene that plays a prominent role in tumor growth and metastasis by acting in concert with other ERBB (human epidermal growth factor receptor) family members, such as ERBB2 and ERBB35–8." (PMID 28600491, 2017). "The gross images of tumor tissues revealed that the smallest residual tumor volume was in the anti-EGFR-GN+NIR-PTT group." (PMID 29156817, 2017). "The reason for this was clearly that some tumor-tissue EGFR M+ patients were detected as false negatives in cfDNA tests." (PMID 28052016, 2017). "Amplification of EGFR was verified in single cells from tumor imprint specimen and in cells after 6 passages of adherent culture in EGF supplemented media." (PMID 28148893, 2017). "Recently, primary tumor location of CRC was reported to be associated with the efficacy of cetuximab, a monoclonal antibody targeting epidermal growth factor receptor (EGFR)." (PMID 29108341, 2017).
tumor (continued). "The second major reason for our limited understanding of the EGFR physiology and pathophysiology is the lack of quantitative, high-resolution studies of endocytosis and signaling of endogenous EGFR in vivo, particularly, in tumor models." (PMID 29268862, 2017). "Icotinib is a novel and the third listed epidermal growth factor receptor-tyrosine kinase inhibitors (EGFR-TKIs), which exerts a good anti-tumor efficacy on non-small cell lung cancer (NSCLC)." (PMID 28430623, 2017). "Neither PEG engagerEGFR nor PEG engagerCD19 enhanced the fluorescence signal in HepG2 (low EGFR expression levels) tumour-bearing mice." (PMID 28593948, 2017). "Immunofluorescence labeling of early endosomes and phosphorylated EGFR in HSC3/EGFR-GFP flank tumor xenografts." (PMID 29268862, 2017). "The ErbB family receptors, including EGFR (ErbB1), HER2 (ErbB2), HER3 and HER4 are most frequently implicated in neoplasia and are known to turn on the PI3K/AKT pathway to regulate cell proliferation, survival, angiogenesis, migration and invasion." (PMID 29066975, 2017). "The levels of EGFR would soon be found to predict tumor grade, patient prognosis, and relapse in cancer." (PMID 28513565, 2017). "Cells accumulating H-1PV transcripts and NS1 were found mainly in areas staining positive for glial fibrillary acidic protein (GFAP) and epidermal growth factor receptor (EGFR) expression, suggesting virus replication in tumor cells." (PMID 28967558, 2017). "The present meta analysis have several strengths: First, we first revealed that high EGFR expression is significantly correlated with tumor differentiation, lymph node metastasis, and tumor stage." (PMID 28199988, 2017). "Our xenograft data suggested that suppression of tumor growth and metastasis occurs through the inhibition of the proliferation and the induction of apoptosis of the tumor cells, indicating the potential for miR-34a as a strategy for EGFR-targeted therapy." (PMID 28825720, 2017). "BiTEs have been designed to target a variety of tumor antigens such as CD19, EphA2 receptor tyrosine kinase, EpCAM, EGFR, melanoma-associated chondroitin sulfate proteoglycan, and CD33, among others, and have shown therapeutic efficacy in mouse tumor models." (PMID 28938530, 2017). "A phase IV, open-label, single-arm study in Caucasian NSCLC patients (N = 652) demonstrated 94% concordance for EGFR mutations detected (by ARMS, Qiagen) between plasma and tumor tissue in a study evaluating efficacy and safety of gefitinib." (PMID 29246024, 2017). "Herbst and co-workers evaluated the percentage of increased EGFR expression within some tumor types." (PMID 29271876, 2017). "EGFR overexpression was assessed based on membrane staining, which showed strong intensity widely in the tumour area." (PMID 28653173, 2017). "Aberrant EGFR overexpression is frequently observed in NPC, and is associated with tumor metastasis, recurrence, and poor survival in NPC patients." (PMID 28157708, 2017). "pEGFR is a byproduct of EGFR activity, and can serve as a preliminary indicator of the efficacy of EGFR TKIs against tumor cells." (PMID 29228726, 2017). "Tumor size and pathologic stage were comparable between the EGFR mutant group and the wild-type group." (PMID 29065153, 2017). "The expression of IL-13Rα2 and EGFR proteins was confirmed in primary tumor samples from Singaporean patients with GBM." (PMID 29203859, 2017). "For this reason, tumor tissue, where available, should be the first sample of choice for EGFR testing to provide an initial molecular diagnosis, to determine if patients are suitable for TKI therapy." (PMID 27980215, 2017). "Immunohistochemistry analysis of the tumor was performed for 10 patients (Ki67, pERK, pAKT, EGFR and pEGFR)." (PMID 27764781, 2017).
tumor (continued). "Recently, the combination of CDK4/6 and EGFR inhibitors has been shown to be effective in blocking tumor resistance in mice." (PMID 28513565, 2017). "Tumor recurrence was observed in 46 patients (36 [41.4%] in the EGFR mutant group and 10 [30.3%] in the wild-type group; p = 0.3)." (PMID 29065153, 2017). "Afatinib is an irreversible kinase inhibitor targeting epidermal growth factor receptor (EGFR) and inhibiting tyrosine kinase auto-phosphorylation to stop tumor cells growth." (PMID 31725865, 2017). "Immunohistochemical expression of uPAR, TF and EGFR in tumor resection specimens from 191 patients with primary OSCC was analyzed." (PMID 28841839, 2017). "IGF2BP3 is upregulated by EGFR, which promotes tumor cell migration and invasion by inducing expression of pre-migration/invasion genes." (PMID 29088808, 2017). "In a recent mouse study, the smaller anti-EGFR affibody protein (±7kDA) had a significantly higher concentration in the tumor periphery than the full antibody (±150 kDa)." (PMID 27878374, 2017). "Epidermal growth factor receptor (EGFR, ErbB-1 or HER1) over -expression can be detected on numerous epithelium-originated tumor cells, especially those generated from respiratory and digestive systems." (PMID 28445134, 2017). "This F2-7 cell line-derivative retained expression of EGFR as its BM-PDXs counterpart, and retained tumor initiating capability in vitro (measured as ability to form colonies in the absence of extracellular matrix in mammosphere assays, not shown)." (PMID 29164052, 2017). "In NSCLC tumor cells resistant to the EGFR TKI gefitinib the expression of CXCR4 maintains stemness through JAK/STAT3 downstream signaling." (PMID 28402937, 2017). "Although it is known that the immediate target of lapatinib is the ATP-binding pocket of ErbB2 and EGFR kinase domains, it has been demonstrated that modulation of specific intracellular targets can enhance or block lapatinib-induced anti-tumor activities." (PMID 28938602, 2017). "By increasing body temperature using an OXPHOS uncoupling agent (thyroxine sodium) in combination with EGFR pathway inhibition, we achieved significant tumor growth inhibition." (PMID 28915593, 2017). "In agreement with our in vitro data, PTX treatment induced elevated expression levels of MUC1, ABCB1, and marked increase of EGFR nuclear localization in tumor tissues." (PMID 28796259, 2017). "In a combined human and animal ex vivo study, labeling quantum dots (QDs) with EGF and anti-EGFR antibodies visualized individual tumor cells with confocal imaging reaching a TNR as high as 1000, even for LGGs." (PMID 27878374, 2017). "Between December 2007 and April 2011, tumor samples from 149 patients were subjected to the molecular screening for the number of the EGFR gene copy number." (PMID 27924059, 2017). "Restoring miR-16 also re-sensitised MPM cells to pemetrexed and gemcitabine and the intravenous administration of miR-16 in nanocells with epidermal growth factor receptor (EGFR) specific antibodies, inhibited tumour growth in mice." (PMID 29100460, 2017). "In the PDECX1T0950 model, a dose response (2, 5 and 15 mg/kg) was observed, suggesting that anti-tumor activity was dependent on the level of inhibition of EGFR pathway activation." (PMID 28881608, 2017). "We analyzed the presence of mutations in exons 18 to 22 of EGFR and of exon 2 of KRAS in tumors, where the mutation of the KRAS gene was detected both in LLC cell culture and in the tumor implants extracted from the mice." (PMID 29285236, 2017). "Four patients (4/215, 1.9%) who were tumor-tissue EGFR M- but plasma EGFR M+ were enrolled in our study, and three of them benefited from EGFR-TKI treatment." (PMID 28052016, 2017). "This has been shown to reduce renal uptake of a 99mTc-labeled anti-EGFR nanobody by 45% in tumor xenografted mice." (PMID 29213270, 2017).
tumor (continued). "Even though certain EGFR IgG1 monoclonal antibody combinations such as Sym004 and MM-151 showed superior anticancer efficacy in several human tumor xenograft models, their effects on ADCC were only investigated in EGFR amplified cell lines." (PMID 28467975, 2017). "Panitumumab is a recombinant human mAb that binds specifically to the extracellular domain of EGFR on both normal and tumor cells, and competitively inhibits the binding of ligands for EGFR." (PMID 28219375, 2017). "In the current study, we retrospectively investigated the patterns of disease progression and the feasibility of re-biopsy of targeted relapsing tumor lesions following the development of EGFR-TKI resistance in patients with NSCLC." (PMID 29212495, 2017). "Further studies with a larger representation for each TGCT subtype would be needed to evaluate the prognosis value of EGFR expression in these tumours." (PMID 28320414, 2017). "The anti-EGFR affibody molecule was present in the tumor periphery whereas the anti-EGFR antibody was primarily localized in the central portion of the tumor." (PMID 27379987, 2017). "40% to 50% of patients with MET-amplified esophagogastric cancer harbor co-amplification of HER2 and/or EGFR concurrently in the tumor cells, which can drive de novo resistance." (PMID 28806950, 2017). "This highlights the importance of understanding how trafficking of EGFR regulates EGFR signaling and the extent to which the subcellular distribution of EGFR predicts tumor cell fate." (PMID 28646091, 2017). "miR-200a, the anti-tumor microRNA, is able to inhibit the epithelial-mesenchymal transition and reverse the resistance to anti-EGFR therapy." (PMID 28057023, 2017). "We observed that the anti-tumor effect of EGFR inhibitors was more pronounced when the mRNA expression of STs was lower (left side of heat-map)." (PMID 28423672, 2017). "Multivariate Cox regression analysis revealed that tumor stage IV and wild-type EGFR status were independent prognostic factors for worse PFS." (PMID 27863417, 2017). "The expression of several biomarkers in pretreatment biopsies, such cyclin D1, p21, EGFR and VEGF have been associated with tumor response to nCRT." (PMID 28938543, 2017). "Another possible reason is the improved delivery of EGFR‐TKIs due to normalization of the tumor microenvironment." (PMID 28388009, 2017). "Many studies have reported nuclear transport of EGFR in cultured tumor cells exposed to ligand, X-rays, UVC or cisplatin." (PMID 28646091, 2017). "The anti-EGFR Apt-QLs exhibited remarkable EGFR-dependent siRNA delivery as well as fluorescence imaging, which were analyzed in cultured cancer cells and tumor xenografts in mice." (PMID 28842588, 2017). "Here the authors show that sortilin limits cell proliferation and tumor growth by promoting EGFR internalization." (PMID 29084952, 2017). "CRIS-D groups a subset of tumours enriched for IGF2 overexpression, which has been recently implicated in desensitization to EGFR blockade in patients with KRAS wild-type tumours." (PMID 28561063, 2017). "EGFR-TKIs such as gefitinib or erlotinib inhibit tumor cells by blocking the EGFR signaling via binding to ATP binding site of EGFR to increase survival in NSCLC patients." (PMID 28430623, 2017). "In a cohort of patients whose archival tumor was KRAS WT and consequently received anti‐EGFR therapy, KRAS mutations were detected by BEAMing in the plasma of 48% of patients at disease progression." (PMID 28106345, 2017). "EGFR signaling is frequently enhanced in cancer, affecting tumor cell proliferation, angiogenesis, apoptosis, differentiation, and immune responses." (PMID 28801576, 2017). "It has already been demonstrated in a mouse model of B16 melanoma that combined therapy of tumor immunization with EGFR antagonist treatment improves the efficacy of either treatment alone." (PMID 28970798, 2017).